GZMB (granzyme B)
Diseases named in the same sentence as GZMB in open-access papers (continued):
Sharing a sentence is not in itself a finding about the gene and the disease.
cancer (continued). "The cancer cell rapidly creates a large vacuole around the NK cell, which obstructs the penetration of granzyme B into the cytoplasm and forces the NK cell to re-endocytose granzyme B, leading to its death via an apoptotic pathway." (PMID 34685548, 2021). "Perforin (Prf1) and granzyme B (GzmB) are key cytotoxic effectors that kill cancer cells for NKs." (PMID 33868269, 2021). "Given the excellent in vitro results, we examined whether probe 1 could be used to detect granzyme B‐mediated activity of NK cells against cancer cells under a PhotonImagerTM luminescence imaging system." (PMID 33300671, 2021). "B cells can also produce granzyme B, which can kill cancer cells directly." (PMID 33513935, 2021). "To address whether this observation is specific to CRC, we investigated the correlation of GZMB expression with the T-effector, NK and pDC cell signatures in the TCGA dataset covering 14 cancer types." (PMID 34972191, 2021). "Subsequently, RNA-seq data showed that depletion of LINC02474 might affect the expressions of cancer-related genes, such as GZMB." (PMID 33898319, 2021). "The core module of cytolytic effector molecules appears largely conserved across murine and human viral, human aging, and human cancer contexts: notably, GZMB+ cytotoxic CD4+ T cells co-express GZMA and often GZMH, PRF1, FGFBP2, and granule-associated proteins NKG7 and (in humans) GNLY." (PMID 34910940, 2021). "It has been reported that natural killer (NK) cells and cytotoxic T lymphocytes could kill cancer cells by releasing granzyme A (GZMA) to cleave GSDMB and granzyme B (GZMB) to directly cleave GSDME to activate pyroptosis in cancer cells." (PMID 34616734, 2021). "However, only very few studies have focused on the role of GZMB in cancer cells, even less in CRC cells." (PMID 33898319, 2021). "Moreover, B cells are not only cellular precursors of antibody-producing plasma cells in the TME, but they also act as antigen-presenting cells and are also capable of directly killing cancer cells through the release of granzyme B." (PMID 33494389, 2021). "In this study, we hypothesized that specific granzyme B degraded type IV collagen fragments are released to the circulation and may have a biomarker potential of identifying cancer patients that respond to ICI therapy." (PMID 32998446, 2020). "CD8+ T cells are mounting to cancer responses by releasing perforin, granzyme B, and IFN-γ." (PMID 33093811, 2020). "GZMB is currently used as an indicator of CTL activation in tumors, and its positive immunostaining is associated with a favorable clinical outcome in a variety of cancers." (PMID 32764784, 2020). "In the peritoneum of mice injected with IL-15Rc-secreting cells we detected 10-fold elevated numbers of GrzB+NK1.1+ cells, consistent with the hypothesis of Granzyme-B-mediated killing of cancer cells by IL-15Rc-activated NK1.1+-cells." (PMID 31856922, 2019). "When cancer cells were treated in vitro with lidocaine at clinically relevant concentrations, NK cell cytotoxicity was augmented via the release of lytic granules that contained perforin and granzyme B." (PMID 28905322, 2017). "We have developed mutated versions of these effector proteins to increase their potency, e.g. the granzyme B point mutant R201K is resistant to the natural granzyme B inhibitor serpin proteinase inhibitor 9 (PI-9), thus increasing its pro-apoptotic effect against target cancer cells." (PMID 28704435, 2017). "Taken together, these results indicate that direct cytotoxicity of MAIT cells against cancer cells may be mediated via degranulation of granzyme B and perforin." (PMID 27517754, 2016). "Granzyme B expression was considerably higher within the cancer cell nests of MSI-H tumors." (PMID 20385003, 2010). "Our finding extends the recent paradigm-shifting trend for a more diverse biological role of granzyme B, and might provide a rational basis for exploring its potential prognostic value in a variety of human cancers." (PMID 12838314, 2003).
cancer (continued). "However, the GZMB expression differ between different cases of the same cancer type." (PMID 40766321, 2025). "Indeed, the major granzyme players (GZMB and GzmA) have been shown to regulate angiogenesis and both vascular or extracellular matrix remodeling, which are important not only in tissue repair or organ development, but also in cancer progression." (PMID 40766321, 2025). "This investigation highlighted the diverse associations between DNA methylation of GZMA, GZMB, GZMK, and PRF1 and survival outcomes, displaying the potential prognostic implications of epigenetic modifications in immune-related genes across different cancer types." (PMID 40002821, 2025). "However, on the other hand, this process may also contribute to promoting cancer cell survival, including through autophagic degradation of granzyme B." (PMID 40766321, 2025). "Interestingly, SPAG5 overexpression was correlated with high levels of lymphocyte CD8+, macrophages, neutrophils, dendritic and B cells, positively associated with PD-1/PDL1, LAG3, GZMB and CTLA4 and SPAG5 antigens were suggested as valid immune stimulatory targets for anti-cancers therapy." (PMID 39164278, 2024). "In addition, they can directly kill cancer cells by exhibiting cytotoxic activity via the activation of the Fas/Fas L pathway and the secretion of cytolytic molecules, such as granzyme B (GZMB) and tumor necrosis factor-related apoptosis-inducing ligand (TRAIL)." (PMID 38203530, 2023). "We further found that high expressions of GSDMD and GZMB displayed favorable prognosis in OC from six cohorts (P = 0.034 and P = 2.08E-5, respectively), GSDMD and GZMB were significantly associated with the expression of immune checkpoint molecules with pan-cancer analysis." (PMID 36707884, 2023). "Breg cells affect immune cells such as T cells and NK cells or cancer-associated fibroblasts (CAFs) by secreting anti-inflammatory IL-10, IL-35, and TGF-β or by expressing cell-membrane bound immune-checkpoint molecules, including PD-1, PD-L1, and granzyme B (GrB) in solid tumors." (PMID 37033931, 2023). "Trm cells can release effector molecules and cytokines, such as interleukin-2, interferon-gamma (IFN-γ), tumour necrosis factor-α, and granzyme B. Sustained high expression of these factors may enable Trm cells to rapidly and strongly respond against cancer cells." (PMID 36869093, 2023). "When ovalbumin-expressing cancer cells were cocultured with OT-I T cells, we observed that OT-I T cells were able to kill more sgSlc4a4 cells than sgNT cancer cells (control), together with an increase in cytotoxicity markers such as IFNγ and granzyme B (GZMB)." (PMID 36522548, 2022). "HDAC3-deficient CD8+ cells enhance granzyme B expression and anti-viral effects in a chronic viral infection model, suggesting that HDAC3-targeted inhibition is a potent therapeutic treatment against cancers via enhancement of cytotoxic molecule actions against cancer." (PMID 35163049, 2022). "Importantly, BAY-I, but not BAY-D, treatment could break “the immuno-protective barrier” and promote CD8+ and GZMb+ cells penetration into cancer acini." (PMID 35013322, 2022). "Our results suggested that CD4+ GzmB+ T cells could be a potential target for cancer immunotherapy." (PMID 34631551, 2021). "Considering the four selected peptides increased CD8+ T cell expression of perforin and granzyme B, which play critical roles in the direct elimination of virus-infected or cancer cells, it was subsequently determined whether these peptides also induced CTL responses in vivo using CTL assay." (PMID 34630356, 2021). "Granzyme B (GzmB) as secreted by CD8+ T lymphocytes and could cause cancer cell apoptosis." (PMID 34718325, 2021). "For cytotoxic T-cells that form GJ with cancer cells leading to an enhanced granzyme B activity in cancer cells it was thought that granzyme B or Ca2+ may be transferred and macrophages that communicate via GJ with epithelial cells seem to mediate cGAMP via intercellular channels." (PMID 33192611, 2020).
cancer (continued). "Taken together the decreased TCR stimulation, low granzyme B secretion and impaired cytotoxicity of in vitro and in vivo primed T cells by intratumoral Wnt1-cDCs, these data collectively show that Wnt1 suppresses the ability of cDCs to cross-prime T cytotoxic cells against cancer-specific antigens." (PMID 30926812, 2019). "Also, the GzmB protein was utilized for its capacity to mediate cancer cell apoptosis." (PMID 28181831, 2017). "Although the combination of hypoxia and cancer cell/CAF-derived factors enhances IFNγ and granzyme B expression in CD8+ T cells on a per-cell basis, the overall number of functional effector T cells is markedly reduced." (PMID 42192869, 2026). "As indicated by the release of granzyme B (GrB) and interferon gamma (IFNγ), co-culture of αPD-L1-γδ T cells with OVCAR-8 cancer cells induced T cell activation." (PMID 40842867, 2025). "To determine the prognostic implications of GZMA, GZMB, GZMK and PRF1 across the different cancer types, we explored their Kaplan–Meier plots." (PMID 40002821, 2025). "Δ Ecto, EphA2-79, and EphA2-85 CAR-T cells, and target cancer cell lines were cocultured to measure interferon (IFN)-γ, tumor necrosis factor (TNF)-α, and Granzyme B, cytokines secreted via killing target cancer cells, using ELISA." (PMID 40181964, 2025). "In conclusion, our study underscores the multifactorial impact of GZMA, GZMB, GZMK and PRF1 and their potential as biomarkers for personalized cancer immunotherapy." (PMID 40002821, 2025). "BMDMs or THP-1 cells from WT cancer cells suppressed the proportion of activated CD8+ T cells, as indicated by Ki67, IFN-γ, and GZMB expression, compared to those from ENO1-KO cancer cells." (PMID 40665335, 2025). "Focusing on the co-stimulatory signals, we found that the PVR-TIGIT signaling axis, primarily received by GZMB+ CD8+ T cells and Tregs, is significantly upregulated in VPS25high cancer cells." (PMID 40149859, 2025). "Our findings align with those of recent studies emphasizing the significance of immune-related genes, specifically GZMA, GZMB, GZMK and PRF1, in cancer pathogenesis and clinical outcomes." (PMID 40002821, 2025). "It is possible that CD4+ T28zT2 T cells recognized cancer cells via NKG2D, formed immunological synapses, and delivered IFN-γ and Granzyme B specifically to cancer cells through the immunological synapses." (PMID 40107245, 2025). "Our results demonstrate that Tex markers are consistently expressed at varying levels, while the effector genes (IFNG, GZMB, and PRF1) show lower expression levels across most cancer types." (PMID 40076932, 2025). "In summary, the CNV analysis of GZMA, GZMB, GZMK and PRF1 across multiple cancer types highlighted a remarkable prevalence of heterozygous amplifications and deletions compared to homozygous variations." (PMID 40002821, 2025). "Enhanced T cell activity promotes cancer cell death through effector mechanisms involving perforin (PFN), granzyme B (GzmB), interferon-gamma (IFNγ), and tumor necrosis factor-alpha (TNFα)." (PMID 40806510, 2025). "As a comprehensive pan-cancer exploration, we next investigated the impact of DNA methylation of GZMA, GZMB, GZMK and PRF1 on survival outcomes." (PMID 40002821, 2025). "Further analyses showed that these high HLA‐DR+ cancer cell tumors exhibited elevated levels of LAG3, TNFRSF9, CTLA4, PDCD1, TIGIT, ITGB2, and GZMB." (PMID 40464412, 2025). "NK cells cocultured with the indicated cancer cells were collected and subjected to flow cytometry to analyze the proportions of CD56-, IFNγ-, and granzyme B (GZMB)-positive NK cells." (PMID 39402211, 2025). "A pathway analysis was conducted to evaluate the inhibitory and activating effects of ten cancer-related pathways on the expression of GZMA, GZMB, GZMK and PRF1." (PMID 40002821, 2025). "In the VPP cancers, significant increases were observed in CXCL1, CXCL2, GZMB, IL6, CCL13, and CCL19, among others." (PMID 40361362, 2025).
cancer (continued). "For GZMB, heterozygous deletions were dominant in UCS, MESO, READ and KIRC, emphasizing their significance in these cancers." (PMID 40002821, 2025). "By Day 13, NK cell efficacy indicators, granzyme B and IFN‐γ, along with IL‐17E, significantly increased, indicating enhanced activity and potential for combating cancer." (PMID 40533418, 2025). "Single-cell dataset analysis further indicated that cancer stem cells, CD4+ memory cells, regulatory T cells, NK cells, fibroblasts, and neurons participate in the regulation of related genes, with GZMB serving as a marker for NK cells." (PMID 38846945, 2024). "The engineered NK cells have demonstrated robust antitumor activity, with dose‐dependent eradication of cancer cells and an increase in cytokine secretion, including significant IFN‐gamma and Granzyme B levels." (PMID 39328262, 2024). "In agreement with prior work in a cancer model, we found that CD49dhigh CD8+ T cells exhibit greater cytotoxic potential than CD49dlow CD8+ T cells within TBI mouse brains as indicated by Granzyme B and Ly6C expression (Fig. 5Cii and iii)." (PMID 39427160, 2024). "The phenotype changes of NK cells in ER+/HER2−BC after overexpressing S100A9 in cancer cells were evaluated by the production levels of IFN-gamma, perforin and granzyme B and cytotoxicity assay." (PMID 38713229, 2024). "Co-culture experiments showed MAN’s ability to increase CD8+ Granzyme B (GZMB)+ T cells and decrease CD8+PD-1+ T cells, indicating an anti-cancer effect through blocking the PD-L1/PD-1 signaling." (PMID 38791372, 2024). "Remarkably, we observed an increased proportion of CD8+ T cells expressing activation markers CD69, Granzyme B, and IFN-γ exclusively in the presence of T-DXd-treated cancer cells." (PMID 39449023, 2024). "GzmB+CD4+ T cells have recently been shown to play a role in immune-mediated killing and therapy response in cancer." (PMID 38968186, 2024). "Pentamidine enhanced T-cell-mediated cytotoxicity against various cancer cells in vitro by increasing the secretion of IFN-γ, TNF-α, perforin, and granzyme B in the culture medium." (PMID 37205112, 2023). "ZNF683+ Trm cells, identified as cancer-specific Trm cells in this study, have higher IFNG and GZMB expression compared with ZNF683– Trm cells, suggesting that cancer-specific Trm cells have high cytotoxic potential." (PMID 36869093, 2023). "In the sole B2MMUT case that still contained cancer cells after treatment with ICB, the majority of granzyme B+ immune cells infiltrating the tumour epithelium were γδ T cells." (PMID 36631610, 2023). "Memory B cells have also been reported to possess cytotoxic functions against cancer cells by secreting IFN-γ, granzyme B, and TRAIL." (PMID 37894300, 2023). "Higher expression of proteins associated with T cells, B cells, NK cells, and macrophages (such as GZMB, FOXP3, PD-1, CD20, CD56, and CD68) were observed in the ‘immune-rich cancer cell islets’ cf. ‘surrounding stromal leukocyte’ regions." (PMID 37046826, 2023). "In our study, we identified the expression of GZMB, CD56, and the regulatory T cell (Tregs) marker FOXP3 within ‘immune-rich cancer cell islet’ regions." (PMID 37046826, 2023). "The released granzyme B and perforin trigger caspase‐3/GSDME‐induced cancer cell pyroptosis to achieve CAR‐T‐cell cancer therapy." (PMID 37125240, 2023). "Granzyme B secreted by NK cells cleaves GSDME directly or activates caspase‐3 to cleave GSDME indirectly, inducing the pyroptosis of GSDME‐expressing cancer cells." (PMID 37125240, 2023). "On the other hand, Ad‐loaded NK cells showed a higher immunotoxic effect than unloaded cells, providing a powerful supplement to Ad‐mediated cancer cell killing, owing to the activation of the STAT4‐granzyme B‐dependent pathways." (PMID 34747156, 2022).
cancer (continued). "Significantly upregulated PRGs included PYCARD in 12 cancers; GSDMB in 10 cancers; IL18 in 9 cancers; GSDMD, CASP8, GZMB, and GPX4 in 8 cancers; AIM2 and CASP6 in 7 cancers; GZMA in 6 cancers; GSDME, CASP4 and DHX9 in 5 cancers; GSDMA and GSDMC in 4 cancers." (PMID 36605187, 2022). "Generally, administration of systemic concentrations of selected bacterial metabolites, which can be seen in cancers distal from the gut, increased the numbers and viability of CD8+ T cells and increased production of granzyme B." (PMID 35705580, 2022). "The expression levels of CXCL12, THBS1, PPBP, GZMB, CD74, and UNC93B1 were higher in the cancer group than in the normal group." (PMID 36211454, 2022). "The current findings showed that the expressions of multiple immune-related genes, including CXCL9, CXCL10, GZMB, and PDCD1LG2, were upregulated in cancer with high TME scores." (PMID 35242245, 2022). "SNX-482 was also shown to upregulate the expression of CCR4 (C-C motif chemokine receptor 4), IFNG (IFN-gamma), GZMB (granzyme B) and PDCD1 (programmed cell death protein 1) genes, which are important for anti-cancer activity." (PMID 36119523, 2022). "At present, the relationship of RIPK2 with GZMB, NKG7 and PRF1 in cancer is still unclear, and this still needs to be explored in the occurrence, development, treatment and prognosis of cancer." (PMID 35473583, 2022). "Expression of Granzyme B and perforin and incretion of IFNγ of DNT cells were also involved in the cytotoxicity to cancer cells, which is a classical method to exert antitumor efficacy." (PMID 35894707, 2022). "Further analysis revealed a significant decrease in antitumor factors (GZMA, GZMB, NKG7, and PRF1) in CD8T cells and an increase in the proportion of cancer cells, especially in the cancer-cell-dominant group." (PMID 36497182, 2022). "A majorly pan-cancer positive correlation between promotor methylation and gene expression of GSDMA, CASP1, NLRP9, GZMB, DHX9, DDX3X, SFRS2IP (CASP11) and GPX4 was observed." (PMID 36605187, 2022). "The fact that we observed GZMB expression exclusively in in vitro CRC CMS2 and melanoma tumor cells across a cell line panel covering 12 cancer types emphasizes the need for new research on GZMB function in tumors." (PMID 34972191, 2021). "AIM2 was differentially expressed in multiple cancers, including bladder, breast, esophageal, kidney, liver, lung, stomach, and endometrium, as well as CASP5, NOD2, and GZMB." (PMID 34906145, 2021). "Here we show that the activities of perforin/granzyme B and FAS/FASL pathway both participates in the cancer cell lysis by V-aCD3 in vitro." (PMID 33824272, 2021). "The infiltration number of regulatory T cells (Tregs), GZMB+ cytotoxic T cells increased from normalcy to HSIL and fell from HSIL to cancer." (PMID 33694292, 2021). "It is known that the cytotoxic activity of γδ-T cells against virus or cancer cells was determined by the expression of NKG2D and granzyme B (GrB)." (PMID 33777016, 2021). "Perforin and granzyme B are the most important cytolytic effector molecules in CD8+ T cells against infection and cancer cells." (PMID 34461944, 2021). "TCR-signaled CTLs can then induce cancer cell death via multiple pathways, including by degranulation, which releases perforin (PRF)/granzyme B (GZMB), or by upregulation of FasL or TRAIL that signal cancer cell apoptotic pathways." (PMID 32117911, 2020). "In future studies, we will further evaluate the anti-cancer effects of CFP-induced perforin and granzyme B by blocking these proteins." (PMID 33302530, 2020). "Taken together, increased autophagy in cancer cells negatively affects sensitivity toward NK‐ and CTL‐mediated cell lysis through degradation of granzyme B and inhibition of the immunological synapse." (PMID 30302772, 2019). "NSCLC tissue specimens had greater levels of HMGB1 in cancer patients with increased intratumor expression of CD8, IFN-γ, Granzyme B and Perforin." (PMID 30744691, 2019).